MIF (macrophage migration inhibitory factor)
Diseases named in the same sentence as MIF in open-access papers (continued):
Sharing a sentence is not in itself a finding about the gene and the disease.
tumor (continued). "We divided NPC patients into three subgroups based on EBV and HPV status (EBV−/HPV-, EBV+/HPV-, EBV+/HPV+) and investigated MIF, CD11c, CD68, and CD163 IF scores in tumor nest and tumor stroma." (PMID 34407796, 2021). "We showed for the first time that clinically relevant Hsp90 inhibitors decreased MIF levels in CRC and subsequently reduced tumor growth." (PMID 33542244, 2021). "MIF exerts its effects through interaction with CD74, CXCR2 and CXCR4 found on MDSCs and tumour cells." (PMID 33803414, 2021). "The CXCR4/MIF and CXCR4/CXCL12 axis had been reported as the key elements of MSC migration toward tumor cells." (PMID 33933086, 2021). "Macrophage migration inhibitory factor (MIF) acts as a pro-inflammatory cytokine that is considered as a link between chronic inflammation and tumor development." (PMID 34157052, 2021). "rSmeg-hMIF-hIL-7 administration led to decreased MIF and downstream ERK and PI3K/Akt signaling pathways in primary tumor cells." (PMID 34389619, 2021). "The first in vivo evidence in this regard stems from the observation that anti-MIF treatment in mice xenografted with the NB cell lines, EG7, showed increased T cell accumulation in the tumor." (PMID 32155795, 2020). "In the lung with tumor, the RP-G1 patient expressed CXCL-1, ICAM, IL-1ra and MIF while the RP-G3 patient showed those same cytokines but also expressed CD154, IL-23, IFN-γ and PAI-1." (PMID 33109238, 2020). "The oxazoline derivatives MIF inhibitors CPSI-2705 and CPSI-1306 reduced tumor growth and spreading in mouse models of bladder and skin cancer." (PMID 32155795, 2020). "We found that the monocytic subset of MDSCs (M-MDSCs) expressed high levels of the MIF cognate receptor CD74 and was localized in the tumor microenvironment." (PMID 32625208, 2020). "Macrophage migration inhibitory factor (MIF) is a pleiotropic pro-inflammatory cytokine aberrantly expressed in many solid tumors and known to promote tumor progression and metastasis." (PMID 32943608, 2020). "This study sought to investigate the biological effects of specific MIF inhibitor, ISO-1, on the proliferation, migration and invasion of PANC-1 human pancreatic cells in vitro, and on tumour growth in a xenograft tumour model in vivo." (PMID 32317702, 2020). "Consistent with a MIF-dependent inhibition of antigen presentation, co-culture of purified CD8+ T cells with MIF-treated, tumor antigen-pulsed DCs reduced the ability of CD8+ to lyse tumor cells." (PMID 33324425, 2020). "These include tumour promoting molecules such as VEGF to provide anti-angiogenic therapy (e.g., bevacizumab), IL-6, and MIF (macrophage migration-inhibitory factor), immune checkpoint inhibitors (e.g., PD-1 and CTLA-4), as well as TAAs, e.g., HER2." (PMID 32937961, 2020). "In vitro, LSEC‐derived MIF served as a chemoattractant for CRC cells and increased primary tumor growth and metastasis formation in vivo." (PMID 33252863, 2020). "MIF and MUC-16 glycoprotein, expressed in ovarian tumor, are able to down-regulate NKG2D and to interfere with the formation of the synapses between tumor and NK cells." (PMID 32218226, 2020). "miR-451 was found to be down-regulated in ESCC tumor tissue, but up-regulated in ESCC patient serum and serum exosomes; miR-451 overexpression in fibroblasts increased migration and MIF levels in ESCC cells." (PMID 32957712, 2020). "The chemokines CCL20, CCL17, CCL22, RANTES, macrophage migration inhibitory factor (MIF), MCP1, and CCL4, secreted by cancer cells, fibroblasts, and dendritic and myeloid cells, were responsible for their recruitment to the tumor microenvironment." (PMID 32148497, 2020).
tumor (continued). "Other soluble tumor-derived factors such as TGF-β, Macrophage migration inhibitory factor (MIF), MUC-16 and adenosine can impair NK cells." (PMID 32218226, 2020). "Expression of MIF and pNF-κB p65 were also found to be markedly reduced in ISO-1-treated tumour tissues." (PMID 32317702, 2020). "Macrophage migration inhibitory factor (MIF) and macrophage colony-stimulating factor (M-CSF), cytokines that regulate SR-A expression, are present in the CHL tumor microenvironment." (PMID 31714922, 2019). "In conclusion, MIF has a dual role in colon carcinogenesis: at the onset of tumor development, it may help to activate the immune system against tumor cells; on the other hand, increased abnormal production of MIF by the tumor cells can be used as a proliferative advantage at later tumor stages." (PMID 31360118, 2019). "Studies have found that MIF can downregulate the expression of NKG2D on the surface of NK cells and CD8+ T cells, permitting tumor cells to undergo immune escape from NK cells and CD8+ T cells." (PMID 30813924, 2019). "In line with this, it has been shown that MIF is overexpressed in HCCs, and MIF serum levels correlate with tumor size and TNM (tumor/nodes/metastasis) stage." (PMID 31370326, 2019). "The lack of these cells may be the reason why MIF deficiency enables tumor growth." (PMID 31360118, 2019). "The angiogenic activity in tumors was attributed to the fact that MIF acts as a potent inducer of the angiogenic factors VEGF, CXCL5, and CXCL8 in tumor cells." (PMID 31866994, 2019). "This is in line with previous studies documenting the capacity of MIF to induce VEGF and phosphorylation of ERK1/2 in tumor cells." (PMID 31866994, 2019). "The tumor-suppressive miRNAs miR- 451 and miR-539-5p inhibit NPC initiation by targeting the macrophage migration inhibitory factor (MIF) and Kruppel-like factor 12 (KLF12) genes, respectively." (PMID 31456943, 2019). "The results showed that MIF expression was increased dramatically in the metastasis group (p < 0.05) and VEGFA expression positively correlated with tumor grade (p < 0.05)." (PMID 31293831, 2019). "Several studies reported overexpression of MIF and CD74 in multiple cancers and that the MIF/CD74 signaling pathway promotes tumor progression and angiogenesis." (PMID 31866994, 2019). "In particular, inhibition of (IFN)-γ secretion in microglia seems to play a crucial role in the prooncogenic role of MIF, as blockade of MIF/CD74 interaction promotes IFN-γ release and amplifies tumor death." (PMID 29707160, 2018). "Therefore, MIF overexpression may be a protective mechanism used by cancer cells to prevent cell death and overcome the immune response under the stressful conditions experienced within the tumor microenvironment." (PMID 29864117, 2018). "In vitro, MIF expression prevents ICD and also suppresses markers of apoptosis in serum-starved tumor cells." (PMID 29864117, 2018). "MIF transcriptionally downregulates NKG2D in NK cells and lowers the ability of these cells to kill tumor cells." (PMID 30200478, 2018). "Macrophage migration inhibitory factor (MIF) is a structurally unique cytokine with pro-inflammatory and tumor-promoting functions." (PMID 29113309, 2017). "Most recently, it was shown that macrophage migration inhibitory factor (MIF)/CXCR4 and monocyte chemoattractant protein-1 (MCP-1)/CCR2 pathways are responsible for migration of MSCs in the tumor microenvironment of the lungs." (PMID 28798777, 2017).
tumor (continued). "The supression of MIF and PI3/Akt pathway would be certainly involved in tumor suppressive role of miR-451." (PMID 28704499, 2017). "BAX69 abrogates MIF signaling and MIF-mediated secretion of cytokines (IL-1β, TNF-α, etc.)and inhibits proliferation of MIF overexpressing tumor cells, together with the antiproliferative effects of panitumumab (anti-EGFR mAb)." (PMID 29312320, 2017). "We also investigated highly the immunochemical expression of CXCR4, MIF and Bcl-2 in HCT-116/OxR tumor sections." (PMID 27668882, 2016). "Macrophage migration inhibitory factor (MIF) is a pleiotropic cytokine, which was shown to be upregulated in cancers and to exhibit tumor promoting properties." (PMID 27636991, 2016). "There has been observed physical interaction between MIF and CXCR2, CXCR4, and CD74, although only CXCR4 is dominant receptor recognized by MIF in context of tumor homing." (PMID 27630452, 2016). "Decreasing MIF or CD74 expression in H28 and H2052 MPM cells reduced multiplication rate of the tumor cells due to a reduction in proliferation and an increase in apoptosis." (PMID 26883190, 2016). "In the future, in order to clarify the complex role of MIF and/or CD74 from tumor and stromal cells in MPM development, we plan to perform i.pl." (PMID 26883190, 2016). "Immunohistochemical analysis showed that MIF expression was ~2-fold higher, LC3 expression increased significantly by ~4-fold and STAT3 phosphorylation was 1.5-fold higher in ConA-treated tumor lesions compared with the control groups." (PMID 26633714, 2015). "Therefore, the role of MIF in metastasis seems to be ambivalent maybe dependent on tumor type." (PMID 26347749, 2015). "To exclude the effect of MIF from CRC cells themselves, we also knockdown the expression of MIF in CRC cells, the MIF secreted by HHSECs promoted tumorigenesis and tumor growth markedly in nude mice co-transplanted Mock/HHSECs subcutaneously." (PMID 26087187, 2015). "In PDAC, MIF has been shown to induce the EMT, enhance tumor aggressiveness, and predict clinical outcome in resected PDACs." (PMID 26267609, 2015). "Knockdown of MIF in a murine ovarian cancer cell line, ID8 has been shown to decrease tumor growth and increase the survival in tumor transplanted mice." (PMID 26530123, 2015). "Thus, stromal cell production of MIF may have an important impact in the tumor microenvironment." (PMID 24887129, 2014). "Additionally, MIF may interact with cyclin D to promote HCC tumor growth." (PMID 25015194, 2014). "In lung cancer cells, both MIF and D-DT contribute to CXCL8 and VEGF production, two important factors for tumor progression and angiogenesis." (PMID 24406307, 2014). "The most prominent MIF inhibitor, ISO-1, is known to inhibit the proliferation/invasiveness of cancer cell lines in vitro and tumor growth and vascularization in vivo." (PMID 25050663, 2014). "MIF was expressed in the cytoplasm of tumor cells and TILs, and CXCR4 was expressed in the nucleus or cytoplasm and cell membrane of tumor cells and the cell membrane and cytoplasm of TILs." (PMID 23497377, 2013). "The cytokine array data demonstrating production of numerous stromal-interacting cytokines (e.g. TIMP-1, MIF, uPA, Serpin E1/PAI-1, MMP-9) suggests that the xenografts are interacting with and being altered by components of the tumor microenvironment." (PMID 24204737, 2013). "We conducted cell growth inhibitory experiments using the MuSS cell line with a MIF inhibitor and a SCD1 inhibitor to investigate the role of MIF, SCD1, and the combination of MIF and SCD1 for tumor progression." (PMID 24167613, 2013). "We previously showed serum MIF levels to be highly increased in AOSD patients compared with those with infection, neoplasm, and rheumatic arthritis, and in controls." (PMID 23721694, 2013). "In the present study, the protein expression levels of MIF and CXCR4 were examined in tumor specimens from 136 patients with ESCC." (PMID 23497377, 2013).
tumor (continued). "The expressions of MIF and CXCR4 proteins in tumor cells and TILs have different clinically predictive values in ESCC." (PMID 23497377, 2013). "In the current study, Pearson’s correlation coefficient and a linear regression analysis were applied to evaluate the correlations between the expression levels of MIF and CXCR4 in tumor cells and TILs." (PMID 23497377, 2013). "Based on the criteria described in the Methods section, high expression levels of MIF and CXCR4 in tumor cells were noted in samples from 73 (53.7%) and 47 (34.6%) of the 136 patients, respectively." (PMID 23497377, 2013). "These experiments suggest that the combination of MIF and SCD1 is useful as a prognostic marker for tumor progression." (PMID 24167613, 2013). "Thus, interventions that inhibit the effects of MIF (to counteract the primary tumor-derived signal) and or RANTES (to counteract the endothelium derived signal), or block their cognate receptors could possibly offset tumor growth by altering the tumor-induced niche." (PMID 21647415, 2011). "Second, radioiodinated anti-MIF McAb was used as a prospective HCC imaging agent and provided clear image in tumor radioimmunoimaging." (PMID 21438767, 2011). "All 7 primary tumors secreted MIF, 4 tumors secreted IL-8, 3 tumors secreted MIP-1α and only one tumor secreted IL-13 and IL12." (PMID 21647415, 2011). "Thus, MIF could be used as a marker for HCC tumor detection." (PMID 21438767, 2011). "Autocrine MIF promoted tumour cell proliferation, as indicated by blockade of MIF or CD74 in MDA-MB-231 and MDA-MB-468, and MDA-MB-231 invasiveness was enhanced by exogenous MIF." (PMID 19602265, 2009). "Some genes, such as MIF and CCDN2, bore predominant pro-tumor progression functions, other genes, such as KLF5 and TGFBR2, contribute to tumor suppression functions." (PMID 18570662, 2008). "We noticed that MIF is also expressed by other tumor cells in pre-nonresponders that do not express HMGCR." (PMID 41355948, 2026). "We propose that MIF+ tumor cell infiltration within TLS, rather than TLS abundance alone, is a critical co-factor for predicting immunotherapy response." (PMID 41355948, 2026). "Our data demonstrate that tumor cells disrupt GC reactions via MIF-CXCR4 interactions, suggesting that GC evaluation, combined with MIF or HMGCR assessment, could refine biomarkers for immunotherapy sensitivity." (PMID 41355948, 2026). "Through high-resolution spatial analysis of paired pre-/post-treatment tumors, we demonstrated that although GC reactions were activated in non-responders, MIF-expressing tumor cells disrupted canonical CXCL12-CXCR4 signaling via direct MIF-CXCR4 interactions." (PMID 41355948, 2026). "This phenomenon supports our finding that high MIF expression is a key factor driving treatment non-response, indicating that MIF upregulation is a broader phenomenon not restricted solely to the tumor cell subpopulation expressing high HMGCR." (PMID 41355948, 2026). "Binding of MIF to CD74 initiates the intracellular signaling cascades that promote cell proliferation, survival, and resistance to apoptosis hallmarks of malignant transformation that tumor cells readily exploit." (PMID 41597203, 2026). "Taken together, these data firmly establish MIF and MDK as abundantly secreted, tumor-derived immunosuppressive factors which may hamper cytotoxic function of T/NK cells inside and outside the TME." (PMID 39908652, 2025). "These niches are created through various systemic effects, such as the disruption of local fibroblasts, the recruitment of bone marrow-derived cells, and the secretion of macrophage migration inhibitory factor (MIF), which together foster a favorable environment for tumor cell invasion and spread." (PMID 40725201, 2025).
tumor (continued). "Strikingly, this effect was abrogated when ZDHHC9 was silenced or when tumor cells were treated with Imatinib, suggesting that ZDHHC9 activity in tumor cells is required for secreting factor(s) – likely including MIF – that skew macrophages to an alternative (M2) phenotype." (PMID 40740766, 2025). "Moreover, MIF, through binding with CD74 and CXCR4, facilitates tumor cell migration and invasion and regulates the immunosuppressive state in the tumor microenvironment." (PMID 40110199, 2025). "The aberrant activation of the MIF signaling pathway may be an important biological characteristic of the CS1 subtype, potentially impacting tumor progression and immune status." (PMID 40170854, 2025). "While stromal cells theoretically contribute minor amounts of MIF to the tumor microenvironment, our data suggest that this source is not sufficient to sustain tumor growth." (PMID 40835826, 2025). "Notably, several downstream signaling pathways regulated by MIF— including MAPK/ERK, PI3K/AKT, NF-κB, and HIF-1α/VEGF— have been reported to be highly activated in KSHV-infected tumor cells." (PMID 41472252, 2025). "In addition, tumor cell-highCNs closely communicated with CD8 T cells through MIF and human leukocyte antigen (HLA)-related ligand-receptor pairs, and CD8 T cell sent signals to tumor cell-highCNs via CD99–CD99 and ITGB2–ICAM1 interactions (P < .01)." (PMID 40052442, 2025). "To evaluate the potential impact on tumorigenesis of this natural genetic variation in human MIF expression, we examined YUMMER1.7 tumor growth in mice engineered to express the commonly occurring -794 CATT5 low-expression or -794 CATT7 high-expression MIF alleles in place of endogenous murine Mif." (PMID 41122966, 2025). "We next verified whether ablating TAMCs or targeting the MIF‐mediated crosstalk among TAMCs, iCAFs, and T cells under the background of AG neoadjuvant therapy could ameliorate the suppressive TME and its pro‐tumor effects." (PMID 41159485, 2025). "Furthermore, MIF downregulates MHC class II, implying that it also hinders the presentation of tumor antigens to CD4+ T cells." (PMID 41159021, 2025). "Histological analysis of the TAM-treated MifΔ/Δ;TP53Q/Q group at the invasive front revealed that both, tumor cells with high MIF level as well as tumor cells without MIF, are able to invade through the muscularis mucosae independent of Mif recombination." (PMID 40835826, 2025). "Moreover, a previous study demonstrated the effects of CPSI-1306 treatment and MIF reduction in human TNBC grafts, showing a decrease in the infiltration of MDSCs in the tumor." (PMID 41159021, 2025). "Differentiation between SSR4+ and SSR4- cells suggests that SSR4 might regulate the interactions between ESCC tumor plasma cells and TME, possibly by modulating the MIF/CD74/CXCR4 axis." (PMID 40066443, 2025). "Well-known cytokines include Macrophage Activation Factor (MAF) and Macrophage Migration Inhibitory Factor (MIF) produced by T-cells regardless of contact with the tumor cell." (PMID 40821768, 2025). "Interestingly, our results from in vivo blocking assays using 4-IPP, MIF inhibitor and stattic, p-STAT3 inhibitor clearly demonstrated that sizes of tumor from the 4-IPP and stattic injection groups are significantly reduced compared to the control group." (PMID 39891284, 2025). "Consequently, targeting MIF through pharmacological inhibition of HSP90 represents a promising, tumor-selective strategy." (PMID 40835826, 2025). "In LUAD tumor tissues, levels of MIF mRNA and protein were significantly higher than those in normal alveolar EPCs, with elevated MIF mRNA levels in both TCs and premalignant states in LUAD." (PMID 40936936, 2025). "Notably, MIF as an immunosuppressive factor in the TME, promotes tumor progression via an immune evasive environment." (PMID 40861802, 2025). "As expected, the total tumor numbers per mouse had not changed 6 weeks after TAM-induced MIF ablation, because MIF was depleted in established tumors." (PMID 40835826, 2025).